MISFA (mitochondrial sheath formation associated)
Description:
[Isoform Kastor]: Regulates sperm development. May be involved in mitochondrial sheath formation. [Isoform Polluks]: Regulates sperm development. May be involved in mitochondrial sheath formation.
Synonyms: SPTY2D1-AS1; SPTY2D1OS; Kastor; Polluks; TSCL1
Gene: Protein-coding gene on chromosome 11 (18,588,781 to 18,610,255, forward strand). Ensembl gene ENSG00000247595.
Subcellular location: Mitochondrion outer membrane (Isoform Kastor); Mitochondrion outer membrane (Isoform Polluks)
Gene Ontology:
Cellular component: mitochondrial outer membrane
Homologues: Orthologues: macaque MISFA (92% identical).